NRG2 (neuregulin 2)
Description:
Direct ligand for ERBB3 and ERBB4 tyrosine kinase receptors. Concomitantly recruits ERBB1 and ERBB2 coreceptors, resulting in ligand-stimulated tyrosine phosphorylation and activation of the ERBB receptors. May also promote the heterodimerization with the EGF receptor.
Synonyms: DON-1; NTAK; HRG2; DON1
Tractability: Antibody: its Gene Ontology location is reachable by antibodies, with high confidence; UniProt places it where antibodies can reach, with medium confidence; UniProt predicts a signal peptide or a membrane-spanning region.
Gene: Protein-coding gene on chromosome 5 (139,846,779 to 140,043,299, reverse strand). Ensembl gene ENSG00000158458.
Subcellular location: Cell membrane (Pro-neuregulin-2, membrane-bound isoform); Secreted (Neuregulin-2)
Subcellular location (Human Protein Atlas): Nucleoplasm; Nucleoli; Predicted to be secreted
Pathways (Reactome):
Signal Transduction: Downregulation of ERBB2 signaling; Downregulation of ERBB2:ERBB3 signaling; ERBB2 Activates PTK6 Signaling; ERBB2 Regulates Cell Motility; GRB2 events in ERBB2 signaling; GRB7 events in ERBB2 signaling; Nuclear signaling by ERBB4; PI3K events in ERBB2 signaling; PI3K events in ERBB4 signaling; PI5P, PP2A and IER3 Regulate PI3K/AKT Signaling; PIP3 activates AKT signaling; RAF/MAP kinase cascade; SHC1 events in ERBB2 signaling; SHC1 events in ERBB4 signaling; Signaling by ERBB2; Signaling by ERBB4
Disease: Constitutive Signaling by Aberrant PI3K in Cancer; Signaling by ERBB2 KD Mutants; Signaling by ERBB2 TMD/JMD mutants
Gene Ontology:
Molecular function: signaling receptor binding
Biological process: animal organ development; ERBB4 signaling pathway; intracellular signal transduction; signal transduction; nervous system development
Cellular component: nucleolus; nucleoplasm; extracellular region; plasma membrane
Genetic constraint (gnomAD): Loss-of-function variants: 27 observed, 64.15 expected, observed/expected ratio (o/e) 0.42, 90% interval 0.31 to 0.58. The synonymous counts are far from expectation, so gnomAD's model fits this gene poorly and the ratio says little. Missense variants: 1,126 observed, 1,058 expected, observed/expected ratio (o/e) 1.06, 90% interval 1.01 to 1.12. Synonymous variants: 532 observed, 448.1 expected, observed/expected ratio (o/e) 1.19, 90% interval 1.11 to 1.27.
Homologues: Orthologues: chimpanzee NRG2 (99% identical), macaque NRG2 (98% identical), pig NRG2 (97% identical), rat Nrg2 (95% identical), guinea pig NRG2 (73% identical), dog NRG2 (72% identical), mouse Nrg2 (71% identical), zebrafish nrg2b (45% identical), zebrafish nrg2a (32% identical). Paralogues in human: NRG1 (28% identical), NRG3 (14% identical), NRG4 (3% identical).
Diseases named in the same sentence as NRG2 in open-access papers:
NRG2 is named in the same sentence as 30 diseases in open-access papers, as found by Europe PMC text mining. Sharing a sentence is not in itself a finding about the gene and the disease. The quoted sentences say what the papers report.
schizophrenia (15 papers, 2007 to 2024). A major psychotic disorder characterized by abnormalities in the perception or expression of reality. "As the closest NRG1 homolog, NRG2 is involved in increasing susceptibility to schizophrenia from human study through interaction with other NRG and ERBB." (PMID 28993723, 2017). "A single SNP in NRG2 showed significant genotypic association with schizophrenia (SNP RS2936651: map position 139401129 on Chr 5, OR = 2.081, CI 1.156–3.745)." (PMID 17598910, 2007). "Although the direct evidence of the role of NRG2 in the etiology of schizophrenia remains to be determined, the findings of NRG2 on neuropsychiatric disorders are still inspiring." (PMID 33897409, 2021). "A recent study shows that NRG2-KO mice develop dopamine disbalance similar to that observed in schizophrenia and behave abnormally in several behavioral tests, again implying a role of NRG2 in the modulation of behavior implicated in psychiatric disorders." (PMID 31838721, 2020). "To our knowledge, we are the first to examine NRG2 mRNA in the blood in schizophrenia or other psychiatric disorder." (PMID 29163244, 2017). "This study confirms previously published associations between schizophrenia and NRG1 and ERBB4, and points to three other members of the NRG and ERBB gene families (EGFR, NRG2 and NRG3) as potential schizophrenia susceptibility genes." (PMID 17598910, 2007). "Nrg2 knockouts (KO) have higher extracellular DA levels in the dorsal striatum, but lower levels in the medial prefrontal cortex (mPFC), a pattern with similarities to DA imbalance in schizophrenia." (PMID 34072341, 2021). "An interesting and important aspect of our findings of DA imbalance in ErbB4 and NRG2 KO mice, regardless of the underlying mechanisms, is that they are reminiscent of the DA imbalance reported in schizophrenia patients." (PMID 32354758, 2020). "Of these pathways, schizophrenia appears to have to strongest link to the Nrg/ErbB pathway, and SNPs in several of the genes encoding Nrg (NRG1, NRG2, NRG3, and NRG6) and all of the genes encoding ErbB receptors (EGFR, ERBB2, ERBB3, and ERBB4) have been linked to schizophrenia." (PMID 30618607, 2018). "Nrg2 has also been involved in the modulation of schizophrenia-liked behaviors in animal studies." (PMID 28993723, 2017). "In addition to providing further evidence of NRG1 and ERBB4 associations to schizophrenia, our study is the first to suggest possible involvement of three additional genes from the NRG and ERBB gene families, i.e. NRG2, NRG3 and EGFR (ERBB1)." (PMID 17598910, 2007). "However, a recent study showed that ablation of NRG2 in the adult mouse brain mimicked dopaminergic imbalance seen in schizophrenia (i.e., high subcortical dopamine, low cortical dopamine) and resulted in severe behavioral phenotypes relevant to psychiatric disorders." (PMID 29163244, 2017). "Thus, NRG2 may play a role in the pathophysiology of schizophrenia but based on our results seems less likely to serve as a peripheral marker of neurobiological changes found in schizophrenia." (PMID 29163244, 2017).
breast carcinoma (6 papers, 2004 to 2025). "The RBP4/RhoA/Rock1 axis has been found to regulate the proliferation, migration, and invasion of ovarian cancer cells, while NRG2 was identified as a prognostic marker for GC and breast cancer and LBP as a prognostic marker for GC." (PMID 40406134, 2025). "Slattery and coworkers found that NRG2 as a growth factor was involved in progression of breast cancer." (PMID 30123134, 2018). "Previous studies have shown that neuregulin (NRG2) promotes cell proliferation in the subventricular zone via ERBB4 activation, while ERBB4-mediated vasculogenic mimicry has been reported in breast cancer." (PMID 40227858, 2025).
glioma (5 papers, 2018 to 2025). A benign or malignant brain and spinal cord tumor that arises from glial cells (astrocytes, oligodendrocytes, ependymal cells). "We previously demonstrated that NRG2 is highly expressed in grades I-III gliomas and facilitates the migration of human glioma/glioblastoma cell lines, including SHG44, U251, and U-87 MG." (PMID 40584443, 2025). "Furthermore, NRG2 influences the migratory behavior of glioma and glioblastoma cells, significantly enhancing their motility." (PMID 40584443, 2025). "NRG2 is highly expressed in glioma tissues across various grades and modulates the expression of GFAP in glioma cells via the Akt signaling pathway, impacting the prognosis of glioma patients." (PMID 40584443, 2025). "The results showed that NRG1 (p=0.0045), NRG3 (p=0.0073) and NRG4 (p=0.026) were significantly related to survival in recurrent gliomas (all WHO grade), and NRG2 (p=0.031) and NRG3 (p<0.0001) were significantly related to survival in primary gliomas (all WHO grades)." (PMID 34054873, 2021). "Upon looking into the copy number loss of NRG2, NRG3, and BTC in glioma cell lines from CCLE, we found that no copy number loss was observed across glioma cell lines for NRG2 and BTC and copy number loss of NRG3 occurred in approximately 12% of glioma cell lines." (PMID 29342193, 2018).
bipolar disorder (4 papers, 2017 to 2022). A disorder of the brain that causes unusual shifts in mood, energy, activity levels and the ability to carry out day-to-day tasks. "While NRG2 and NRG3 complexes have not been linked to ASD, many reports support their link to other neurodevelopmental disorders such as SCZ and bipolar disorder." (PMID 35501678, 2022).
Cognitive impairment (1 paper, 2021). Abnormal cognition is characterized by deficits in thinking, reasoning, or remembering. "Also, neuregulin mutations have been involved in cognitive impairment in schizophrenic and other neuregulins such as neuregulin 2 have been shown to contribute to the maturation of granule cell neurons, thus indicating a role for neuregulins in the regulation of cognitive tasks." (PMID 33335309, 2021).
Hypertension (1 paper, 2015). The presence of chronic increased pressure in the systemic arterial system. "As ErbB signaling has been implicated in angiogenesis and endothelial cell proliferation, NRG2 might also have relevant role on the development of hypertension." (PMID 26517713, 2015).
juvenile open angle glaucoma (1 paper, 2007). Juvenile glaucoma (JG) is a rare autosomal dominant open angle glaucoma, characterized by early onset, severe elevation of intra ocular pressure of rapid progression, leading to optic nerve excavation and, when untreated, substantial visual impairment. "NRG2 polymorphisms in unrelated patients with juvenile open angle glaucoma and controls." (PMID 17563728, 2007). "NRG2 polymorphisms identified in a family with juvenile open angle glaucoma." (PMID 17563728, 2007).
melanoma (1 paper, 2020). A malignant, usually aggressive tumor composed of atypical, neoplastic melanocytes. "Neither the treatment with recombinant BTC nor that with NRG1 and NRG2 altered the activation of HER3 and STAT3 in A375 melanoma cells." (PMID 33327495, 2020).
myeloma (1 paper, 2010). "The five remaining genes (NRG2, Wnt4, Wnt11, Wnt16 and FGF18) were considered as a "myeloma MGF" although they were not statistically significantly overexpressed in MMC compared to environment cell populations." (PMID 20465808, 2010).
non-small cell lung carcinoma (1 paper, 2018). A group of at least three distinct histological types of lung cancer, including non-small cell squamous cell carcinoma, adenocarcinoma, and large cell carcinoma. "Sun and colleagues found that both NRG1 and NRG2 functioned as ligands of ERBB family and involved in progression of non-small cell lung cancer." (PMID 30123134, 2018).
cancer (7 papers, 2008 to 2024). A tumor composed of atypical neoplastic, often pleomorphic cells that invade other tissues. "When examining the top 100 gene pairs, BSDC1, C3orf14, CDR2L, LRRC42, MEOX2, NRG2, and PLEKHA6, and SCARF1 were consistently identified by feature selection methods to be associated with cancer status." (PMID 33087122, 2020). "Various tumor growth and angiogenic factors including VEGF (vascular endothelial growth factor), bFGF (basic fibroblast growth factor), TGF-β (transforming growth factor β) and NRG2 (neuregulin 2) are regulated by HOXB9 in a variety of cancers." (PMID 28514754, 2017). "C3orf14, CDR2L, LRRC42, MEOX2, NRG2, and SCARF1 have been previously associated with cancer." (PMID 33087122, 2020). "Our study suggests that overproduction of ligands (BTC and NRG2), rather than overproduction of receptors could be the predominant mechanism that the ErbB pathway uses to generate cancer cell proliferation signals." (PMID 18211683, 2008). "Interestingly, C3orf14, CDR2L, LRRC42, MEOX2, NRG2, and SCARF1 are known carcinogenic genes, while BSDC1 and PLEKHA6 have not been described in previous cancer literature." (PMID 33087122, 2020).
psychiatric disorder (7 papers, 2017 to 2024). A disorder characterized by behavioral and/or psychological abnormalities, often accompanied by physical symptoms. "Previously, several linkage analysis and association studies pointed to a genome region encompassing the NRG2 locus to be associated with psychiatric disorders." (PMID 38791584, 2024). "Recently, NRG2 attracted more attention due to its role in the neurogenesis and modulation of behaviors associated with psychiatric disorders." (PMID 31838721, 2020). "NRG2 plays an important role in the development of regional networks in the central nervous system, and the loss of NRG2 may lead to behavioral abnormalities in animals similar to those observed in human psychiatric disorders." (PMID 39744066, 2024). "Like Erbb4 KO mice, Nrg2 KOs performed abnormally in a battery of behavioral tasks relevant to psychiatric disorders." (PMID 34072341, 2021). "Furthermore, several studies have shown that NRG1, NRG2, or genes of the NRG–ErbB network contribute to the etiology of psychiatric disorders." (PMID 38791584, 2024).
tumor (6 papers, 2015 to 2024). "Examples of receptors overexpressed in SCLCs included ERBB3 (tumor ligands NRG1, NRG2) and GDNF receptor 1 encoding GFRA1 (ligand NCAM1)." (PMID 36271074, 2022). "Elevated expression of NRG2 (a ligand of HER/ERBB receptor for activating the EGFR pathway) was found to be correlated with increased tumor aggressiveness." (PMID 34571936, 2021). "Previous studies have shown that tumor growth and angiogenic factors including bFGF, NRG2 and MMP9 promote EMT during tumorigenesis." (PMID 28514754, 2017). "The combined differential tumor versus normal tissue expression of two genes and their vectorial summation correlated with the PFS of three patients treated with afatinib as monotherapy: NRG4 and NRG2 (r = −1 p = 8.4E−04)." (PMID 33911192, 2021).
infection (2 papers, 2011 to 2024). The state of being infected such as from the introduction of a foreign agent such as serum, vaccine, antigenic substance or organism. "More importantly, during N10 infection, MoMFs as senders transmitted signals via Nrg2, which in turn triggered Nrg4 signaling in hepatocytes." (PMID 39599894, 2024).
neurodegenerative disease (1 paper, 2021). A disorder of the central nervous system characterized by gradual and progressive loss of neural tissue and neurologic function. "Although research has demonstrated that NRG1 can promote axonal regeneration and play a neuroprotective role in neurodegenerative diseases, it remains unclear about the biological functions and related mechanisms of NRG2 in neurodegenerative diseases, especially in AD." (PMID 33897409, 2021).
NRG2 also shares sentences with these, for which no sentence is quoted: bladder cancer (2 papers); depression (2); autism (1); autism spectrum disorder (1); colon tumor (1); endometrial cancer (1); epilepsy (1); glaucoma (1); glioblastoma (1); lung carcinoma (1); medulloblastoma (1); neurodevelopmental disorder (1); ovarian carcinoma (1); prostate carcinoma (1); vitiligo (1).